SFRP4 (secreted frizzled related protein 4)
Diseases named in the same sentence as SFRP4 in open-access papers (continued):
Sharing a sentence is not in itself a finding about the gene and the disease.
prostate carcinoma (13 papers, 2012 to 2025). A carcinoma that arises from epithelial cells of the prostate gland. "ST data of 32 prostate cancer tissue samples (N = 8 patients) allowed examination of the spatial distribution of SFRP4, a biomarker we previously have associated with cancer aggressiveness." (PMID 39511287, 2024). "In contrast, other authors reported that cytoplasmic overexpression of SFRP4 was linked to poor prognosis in cohorts of 33–536 prostate cancers." (PMID 32677026, 2020). "To conclude, high SFRP4 gene expression is associated with high Grade Group and recurrent prostate cancer after surgery." (PMID 29079735, 2017). "To conclude, SFRP4 expression is associated with more aggressive disease, and is a biomarker candidate for risk stratification of prostate cancer patients." (PMID 29079735, 2017). "Secreted frizzled-related protein 4 (SFRP4) is a modulator of the cancer-associated Wnt pathway, and previously suggested as a potential marker for prostate cancer aggressiveness." (PMID 29079735, 2017). "Our analyses of multiple independent cohorts in the current study, further support high SFRP4 expression to be associated with more aggressive prostate cancer." (PMID 29079735, 2017). "Conversely, up-regulation of SFRP4 was observed for breast, colorectal and prostate cancers which were associated with an increase in cytoplasmic β-catenin levels." (PMID 22363760, 2012). "This may limit future clinical use of SFRP4 expression for risk stratification in patients with transitional zone prostate cancers, and potentially also in patients with very early stage prostate cancer, and this should be further investigated." (PMID 29079735, 2017). "Absolute quantification of SFRP4 mRNA by real time PCR in biopsies may have a role for risk stratification and treatment selection for prostate cancer patients, including selection of patients for active surveillance and adjuvant treatment." (PMID 29079735, 2017). "Conversely, in gastrointestinal and prostate cancers, sFRP4 is frequently upregulated, where it promotes Wnt pathway activation, invasion, stemness, chemoresistance, and reshaping of the tumor immune microenvironment." (PMID 40891635, 2025). "To understand how SFRP4 relates to prostate cancer we performed comprehensive spatial and multiomics analysis of the same prostate cancer tissue samples." (PMID 39511287, 2024). "For this reason, we investigated the role of SFRP4 by using spatial and multiomics analysis of prostate cancer tissue." (PMID 39511287, 2024). "ST demonstrated that SFRP4 gene expression was predominantly located in the stroma of samples with HG prostate cancer (GG ≥ 3)." (PMID 39511287, 2024). "Increased gene expression levels of secreted frizzled-related protein 4 (SFRP4) is a biomarker in aggressive prostate cancer." (PMID 39511287, 2024). "Several publicly available datasets, including transcriptomics, methylomics and single cell transcriptomics, were used to further investigate and validate the role of SFRP4 in prostate cancer." (PMID 39511287, 2024). "Both the spatial and bulk transcriptomics analysis showed that increased SFRP4 mRNA levels were connected to prostate cancer aggressiveness." (PMID 39511287, 2024). "In contrast, previous IHC staining of the SFRP4 protein in prostate cancer samples predominantly show staining in epithelial cells." (PMID 39511287, 2024). "Decoding the true functions of SFRP4 in prostate cancer progression has proven to be challenging as demonstrated by both this and other studies." (PMID 39511287, 2024). "ST showed that SFRP4 gene expression was predominantly located in the stroma of prostate cancer samples." (PMID 39511287, 2024). "Since then, this connection of SFRP4 and aggressive prostate cancer has been confirmed by several other studies." (PMID 39511287, 2024).
prostate carcinoma (continued). "Leveraging spatial and bulk transcriptomics, DNA methylomics and proteomics on the same prostate cancer tissue samples, this study provides insights on the tissue origin and role of SFRP4 gene expression in aggressive prostate cancer." (PMID 39511287, 2024). "Our results therefore suggest that SFRP4 protein levels were under the limit of detection and are expressed at a substantially lower level than mRNA SFRP4 in our prostate cancer samples." (PMID 39511287, 2024). "To validate if SFRP4 protein levels typically are lower than gene expression, we used the publicly available prostate cancer CPC-GENE datasets which included proteomics (n = 76) and transcriptomics (n = 213) data, of which 63 samples had both omics available." (PMID 39511287, 2024). "A large prostate cancer tissue microarray study identified granular cytoplasmic SFRP4 over-expression positively correlated with aggressive disease, early PSA-recurrence, and genomic instability in ERG negative prostate cancers." (PMID 35204808, 2022). "Another mRNA expression study described SFRP4 as one of the most deregulated genes out of 40 Wnt-pathway related genes analyzed in 54 prostate cancers." (PMID 32677026, 2020). "In prostate cancers, SFRP4 staining was seen in 4529 of our 6980 (64.9%) interpretable prostate cancers and was considered weak in 33.2%, moderate in 23.9%, strong in 7.8% of cancers." (PMID 32677026, 2020). "Functional studies in prostate cancer cell lines further showed that SFRP4 overexpression resulted in a reduced cellular proliferation, anchorage-independent growth, and invasiveness." (PMID 32677026, 2020). "Higher levels of SFRP4 staining in cancer glands as compared to adjacent normal prostate gland demonstrate that SFRP4 upregulations parallels prostate cancer development and progression." (PMID 32677026, 2020). "SFRP4 up-regulation was also been found on the mRNA level in several studies and SFRP4 is part of a commercial prostate cancer gene expression assay to estimate tumor aggressiveness." (PMID 32677026, 2020). "Our initial goal was to generate a gene-expression signature representing sFRP4 activation and to use that signature to identify metabolic targets in breast and prostate cancer through The Cancer Genome Atlas." (PMID 29385093, 2018). "Future studies investigating the role of SFRP4 in prostate cancer bone metastases would consequently be of interest." (PMID 29079735, 2017). "SFRP4 mRNA is over-expressed in primary serous ovarian tumors but decreased in prostate cancers, endometrial stromal sarcomas, lung squamous cell carcinoma and pancreatic tumors." (PMID 29037197, 2017). "Together, this clearly shows significant upregulation of SFRP4 in prostate cancer compared with normal prostate tissue." (PMID 29079735, 2017). "The result of the present study adds substantial validation to SFRP4 expression being increased in prostate cancer." (PMID 29079735, 2017). "We showed SFRP4 gene expression to be increased in prostate cancer compared with normal tissue in five of six cohorts, and in the combined meta-analysis of all cohorts." (PMID 29079735, 2017). "In this study, we have validated the presence of increased SFRP4 gene expression in prostate cancer tissue, and we detected and validated higher SFRP4 gene expression in high Grade Group compared with low Grade Group cancer." (PMID 29079735, 2017). "Overall SFRP4 appears to be a potential biomarker candidate for prostate cancer aggressiveness, and there is a need to validate and clarify the role of SFRP4 in prostate cancer." (PMID 29079735, 2017). "Future studies investigating the mechanistic and clinical usefulness of SFRP4 in prostate cancer are warranted." (PMID 29079735, 2017). "The overall aim of this study was to investigate and validate SFRP4 gene expression in prostate cancer, and its relation to cancer aggressiveness." (PMID 29079735, 2017).
prostate carcinoma (continued). "To conclude, several studies, including the current study, support SFRP4 gene expression to be upregulated in aggressive compared with less aggressive prostate cancer." (PMID 29079735, 2017). "In this study, we performed analyses of SFRP4 gene expression and validated the results in eight independent prostate cancer cohorts." (PMID 29079735, 2017). "To summarise, previous studies have in general reported increased SFRP4 gene expression in prostate cancer compared with normal prostate tissue, but they have been carried out on small cohorts." (PMID 29079735, 2017). "In our study cohort, where metabolic information was available, SFRP4 expression correlated significantly with the concentrations of citrate and spermine, two previously suggested biomarkers for aggressive prostate cancer." (PMID 29079735, 2017). "We successfully validated our key candidate markers in two independent patient cohorts at the transcript level, and further successfully validated the expression of SFRP4 at the protein level using a fourth independent cohort of 536 prostate cancer patients." (PMID 26522007, 2015). "Using an independent cohort of 536 prostate cancer patients we showed SFRP4 expression to be an independent predictor of recurrence after prostatectomy (HR = 1.35; p = 0.009)." (PMID 26522007, 2015). "Tubal epithelium certainly has an epithelial differentiation, and it is known that overexpression of SFRP4 shifts prostate cancer cell lines toward an epithelial morphology." (PMID 22363760, 2012). "However, we and others have identified increased SFRP4 gene expression with increasing prostate cancer aggressiveness, which also have been found for several other cancers." (PMID 39511287, 2024). "Cell cultures may have considerable limitations when investigating the in vivo role of SFRP4 in prostate cancer progression." (PMID 39511287, 2024). "SFRP4 also appears to play a role in prostate cancer, although discrepant findings have been reported as to whether its loss or up-regulation associates with disease progression." (PMID 32677026, 2020). "Although previous findings are controversial, they raise the possibility that the SFRP4 protein may represent a useful prognostic biomarker for prostate cancer." (PMID 32677026, 2020). "However, studies of how SFRP4 regulates the Wnt signalling pathway and other pathways in prostate cancer are necessary before a conclusion can be drawn." (PMID 29079735, 2017). "Interestingly, two studies have shown increased SFRP4 expression in prostate cancer tissue compared with benign prostate hyperplasia, but this approach was not possible to pursue in our study." (PMID 29079735, 2017). "Together, these results underpin SFRP4 as a biomarker candidate of prostate cancer aggressiveness." (PMID 29079735, 2017). "Additionally, SFRP4 gene expression was found to be a predictor of worse outcome in prostatectomy-treated prostate cancer patients." (PMID 29079735, 2017). "However, for prostate cancer, increased gene expression of SFRP4 has been observed, and shown to be a predictor of recurrent disease." (PMID 29079735, 2017). "SFRP4 may therefore potentially be useful in the selection of candidates for active surveillance as well as for patients in need of adjuvant or more aggressive treatment, and SFRP4 deserves further attention in prostate cancer studies." (PMID 29079735, 2017). "For example, cell membrane SFRP4 is reported to correlate with a good prognosis in prostate cancer, suggesting that functional cell membrane SFRP4 bound to Wnt ligands to inhibit activation of the Wnt signalling pathway in prostate cancer." (PMID 23825088, 2013). "Moreover, overexpression of SFRP4 also inhibited proliferation and metastatic potential in prostate cancers and was an independent predictor of outcome." (PMID 22363760, 2012).
prostate carcinoma (continued). "But in the researches of prostate cancer cells in vitro, the overexpression of SFRP1 promotes the growth of BPH1, whereas over-expression of SFRP4 or SFRP3 decreases the proliferation of human PC3 cells." (PMID 36991319, 2023). "The specificity of the SFRP4 antibody was evaluated on western blotting which showed a band at 48 kDa, when tested on protein extracts from PC3 and DU145 prostate cancer cell lines, the predicted molecular weight of SFRP4 being in the range 43-55 kDa." (PMID 26522007, 2015). "It is possible that elevated SFRP4 mRNA is merely a consequence (i.e., passenger) rather than a driver of prostate cancer." (PMID 39511287, 2024). "To conclude, we investigated the biological context of the SFRP4 biomarker by using comprehensive spatial and multiomics analysis of heterogenous prostate cancer tissue, an approach not previously applied to analyze SFRP4." (PMID 39511287, 2024). "In summary, upregulation of SFRP4 is associated with adverse tumor features, genomic instability and poor patient prognosis in ERG negative prostate cancer." (PMID 32677026, 2020). "In conclusion, high SFRP4 immunostaining is associated with poor prognosis and genomic instability in ERG negative prostate cancers." (PMID 32677026, 2020). "The results of our analysis demonstrate that SFRP4 up-regulation is an independent predictor of early PSA recurrence in prostate cancers lacking TMPRSS2:ERG fusions." (PMID 32677026, 2020). "There are only four previous studies including immunohistochemistry of SFRP4 in prostate cancer, and there are no standardised protocols for staining or scoring." (PMID 29079735, 2017). "We did not detect membranous SFRP4 staining of prostate cancer cells in any samples." (PMID 29079735, 2017). "This may be translatable to prostate cancer, and could explain why SFRP4 is not downregulated in cancer." (PMID 29079735, 2017). "SFRP4 may well become an element of such a test for ERG negative prostate cancer." (PMID 32677026, 2020).
glioma (12 papers, 2015 to 2025). A benign or malignant brain and spinal cord tumor that arises from glial cells (astrocytes, oligodendrocytes, ependymal cells). "The expressions of FZD7, along with other two genes, SFRP1 and SFRP4, were identified to be associated with poor prognosis in glioma patients." (PMID 29050331, 2017). "In glioma, high SFRP4 expression is strongly associated with poor outcomes (HR = 3.93 [2.27–6.81], p < 0.0001), while high SFRP2 expression is strongly associated with favourable outcomes (HR = 0.16 [0.09–0.28], p < 0.0001)." (PMID 28218291, 2017). "Therefore, in this study a gain or loss of function of sFRP4 was attempted in glioma cells to have a deeper understanding of its mechanism of action." (PMID 30591679, 2018). "In addition, in glioma, SFRP4 is strongly associated with EMT and angiogenesis gene sets, like in all other cancers." (PMID 28218291, 2017). "The importance of studying Secreted frizzled-related protein 4 (SFRP4) in gliomas is to improve diffuse glioma methylation profiling." (PMID 38993819, 2024). "For example, SFRP4 suppresses glioma stem-like cells through reversing epithelial-to-mesenchymal transition, triggering apoptosis and diminishing cancer stem cell properties." (PMID 35290144, 2022). "Previously, we have reported the ability of sFRP4 to chemosensitize CSCs from glioma and head and neck cancers and improve the response to drugs." (PMID 30591679, 2018). "This would be similar to the effect of sFRP4 in glioma and head and neck cancers, where we demonstrated that it downregulates the proproliferation genes cyclin D1 and c-myc." (PMID 28807014, 2017). "We have shown previously in glioma and head and neck CSCs that sFRP4 inhibits the mesenchymal traits and promotes not only epithelial markers but also morphology." (PMID 28373842, 2017). "Because of the complexity of action of sFRP4 and because of our earlier observation of targeted inhibition of glioma and head and neck CSCs by sFRP4, we decided to investigate further a combination effect of DG with sFRP4." (PMID 28373842, 2017). "Meanwhile, sFRP4 increases chemotherapeutic sensitivity in glioma stem-like cells and induces apoptosis via inhibiting Wnt/β-catenin signalling." (PMID 25844602, 2015). "This may indicate that the Wnt pathway regulates glioma-specific markers in iPSC-derived glioma cells, and conversion was reversed with overexpression of sFRP4." (PMID 37509281, 2023). "The direct role of sFRP4 in regulating apoptosis was observed in the sFRP4 overexpressing and silenced models by virtue of cell death in sFRP4 OE and hyperproliferation in silenced glioma cells." (PMID 30591679, 2018). "As the gain of expression of sFRP4 resulted in prominent apoptosis in glioma cell lines, we analyzed whether there was a role of sFRP4 in apoptosis in the intracellular context and beyond acting via the Wnt pathway." (PMID 30591679, 2018). "As our results indicated an involvement of Wnt antagonist sFRP4 in DG mediated apoptosis consistent with our earlier findings that sFRP4 addition chemosenstitizes glioma stem cells to drugs, we were interested in examining how bCSCs over expressing sFRP4 would respond to DG." (PMID 28373842, 2017). "We observed that in the glioma cell lines, U87MG, U138MG, and U373MG, overexpression of sFRP4 resulted in inhibition of viability and proliferation as measured by MTT and BrdU assays respectively." (PMID 30591679, 2018).